CD163 (CD163 molecule)
Diseases named in the same sentence as CD163 in open-access papers (continued):
Sharing a sentence is not in itself a finding about the gene and the disease.
kidney disease (17 papers, 2016 to 2025). "M2 macrophages expressing CD206 and/or CD163 have been closely associated with kidney fibrosis in human kidney diseases as well as animal kidney diseases." (PMID 38035106, 2023). "However, there is also evidence that CD163-positive macrophages are involved not only in healing after acute injury, but also in the progression of kidney disease." (PMID 38331818, 2024). "Urinary soluble CD163 may be a biomarker of renal disease activity in LN, and its levels vary with LN activity and duration of treatment." (PMID 37334926, 2023). "Consistent with the gene expression of ferroptosis, dysregulation of CD163, PC, and ATP6V0A4 was specific in the glomerular compartment of patients with LN from the GSE104948 cohort compared to other kidney diseases (especially FSGS, MCD, and MGN)." (PMID 37583695, 2023). "On the other hand, as the kidney disease progresses, these macrophages polarize to M2 (CD86-/CD163+/CD206+) which have an anti-inflammatory role promoting the healing of damaged tissue and are therefore considered pro-fibrotic." (PMID 32340145, 2020).
bacterial infection (16 papers, 2009 to 2024). "Although the diagnostic potential of serum CD163 for bacterial infection has been investigated, CSF CD163 has yet to be evaluated for its diagnostic potential for BM." (PMID 35524265, 2022). "CD163 is a scavenger receptor that is associated with M2-like macrophages and mediates anti-inflammatory and anti-microbial events during bacterial infections." (PMID 31121006, 2019). "Therefore, the expression of CD163 is strongly associated with bacterial infection." (PMID 35524265, 2022). "During bacterial infection, to restrict the bacteria from iron acquisition, macrophages take up iron via receptors including hemoglobin‐haptoglobin receptor (CD163), transferrin receptor (TfR) and lipoprotein receptor‐related protein 1 (LRP1)." (PMID 38247172, 2024). "CD163 on macrophages acted as an innate immune sensor and an inducer of local inflammation during bacterial infection." (PMID 37766594, 2023). "Some investigations have also identified CD163 as a macrophage receptor for bacteria and suggested that during bacterial infection, CD163 on resident tissue macrophages acts as an innate immune sensor and inducer of local inflammation." (PMID 24597777, 2014). "Moreover, CD163 sheds from the cell membrane during severe bacterial infection, which would explain lower CD163 expression by isolates from blood but not isolates from V/V-R and, interestingly, CSF." (PMID 37213504, 2023). "In HIV-uninfected children, CRP and PCT were also higher in children with SBI compared to those with no detectable bacterial infection (p<0.0005), and CD163 was higher in non-survivors (p = 0.05)." (PMID 19675669, 2009). "In HIV-infected children, CRP and PCT were higher in children with SBI compared to those with no detectable bacterial infection (p<0.0005), and PCT and CD163 were higher in non-survivors (p = 0.001, p = 0.05 respectively)." (PMID 19675669, 2009).
infectious disease (12 papers, 2012 to 2022). A disorder directly resulting from the presence and activity of a microbial, viral, or parasitic agent in humans. "This is relevant considering that the opposite has been described in other infectious diseases, where CD163 is decreased in C-Mo and T-Mo." (PMID 36969980, 2022). "CD163 is a receptor expressed on monocytes that has been investigated as a potential inflammation marker in different infectious diseases." (PMID 33777054, 2021). "Some of these had been previously associated to a worse prognosis in HIV and other infectious diseases, or related to inflammatory status (IL-6, CD14, CD163, IRAK-M, and TNFα)." (PMID 34211989, 2021). "CD163 has been previously identified as an indicator of disease severity inseveral inflammatory and infectious diseases." (PMID 30970080, 2019). "CD163 is a scavenger receptor that has previously been identified as an indicator of disease severity in several inflammatory and infectious diseases." (PMID 28355218, 2017). "However, the response of CD163 SRCR5-edited pigs to other infectious diseases and their growth, reproduction, and other phenotypic features need to be further characterized to evaluate their potential breeding value and practical application in the future." (PMID 31440241, 2019). "CD163 is a scavenger receptor, expressed exclusively on monocytes and macrophages, that has been investigated as a potential inflammation marker in different infectious diseases." (PMID 28785262, 2017).
adenocarcinoma (10 papers, 2019 to 2025). A common cancer characterized by the presence of malignant glandular cells. "As in both well-differentiated (WD) and poorly differentiated (PD) adenocarcinomas, the protein expression of CD163 was considerably greater than that in paraneoplastic tissues (PT)." (PMID 41142606, 2025). "On the other hand, there was a weak correlation between CD163 and VEGF-C (Pearson correlation r = 0.275, p < 0.001) expression in adenocarcinoma cases." (PMID 33228719, 2020). "Moreover CD163-positive cells were not stained with TTF-1, a marker of adenocarcinoma cells and type 2 pneumocytes that do not contain glycogen (Fig. EV4)." (PMID 39424955, 2024).
inflammation (6 papers, 2013 to 2024). Aberrant reaction of the microcirculation characterized by movement of fluid and leukocytes from the blood into extravascular tissues. "Elevated levels of soluble CD163 (sCD163), an endocytic receptor for haptoglobin-hemoglobin complexes, have been associated with non-calcified coronary plaques and arterial inflammation in individuals living with HIV." (PMID 39311207, 2024). "In the state of vascular inflammation, the complex of HMGB1 and hemoglobin binds to CD163, activating monocytes and promoting the expression of inflammatory factors." (PMID 33997033, 2021).
metabolic disease (6 papers, 2018 to 2023). A congenital disorder (due to inherited enzyme abnormality) or acquired (due to failure of a metabolically important organ) disorder resulting from an abnormal metabolic process. "Consistent data show a role for the TWEAK/FN14/CD163 axis in metabolic disease, chronic autoimmune diseases, and acute ischaemic stroke." (PMID 34542797, 2022). "Here, we review the latest understanding of TWEAK/Fn14/CD163 as one of the chief regulators in immune signalling and its cell-specific role in metabolic disease development and progression." (PMID 34542797, 2022). "This review details the current understanding of the TWEAK/Fn14/CD163 axis as one of the chief regulators of immune signalling and its cell-specific role in metabolic disease development and progression." (PMID 34542797, 2022).
hematological diseases (5 papers, 2023 to 2025). "A soluble variant of CD163 (sCD163), a product of shedding, is present in plasma and other tissue fluids and has been found to be increased in various solid tumors and hematological malignancies, reflecting the increased burden of TAMs overexpressing CD163." (PMID 39996747, 2025). "The hematology B37 database highlights that CTCL has the highest CD163+ cell type among the listed hematologic malignancies." (PMID 37427589, 2023). "We first assessed the Hematology B37 database (QIAGEN Digital Insights) to determine whether gene signatures for M2-like TAMs, defined by CD163 expression, are increased in hematologic malignancies." (PMID 37427589, 2023).
benign tumors (4 papers, 2014 to 2025). "In human, it has been shown that cd163 is involved in formation of benign neoplasm of facial soft tissues and xanthogranuloma." (PMID 31889116, 2019).
kidney (4 papers, 2014 to 2024). "Serum IL-8, IL-8(T) and CD163(IF) were each significantly correlated with post-operative cervical lymph node (LN) metastasis (P = 0.018, P = 0.001 and P = 0.023, respectively)." (PMID 25461761, 2014).
immune diseases (3 papers, 2023 to 2025). "CD163 is a CD163-positive M2-polarized macrophage activation marker, which has been confirmed to be related to various immune diseases." (PMID 37153657, 2023).
neurodegenerative disease (3 papers, 2021 to 2022). A disorder of the central nervous system characterized by gradual and progressive loss of neural tissue and neurologic function. "Among these genes of neurodegenerative diseases, we observed that the NAP1L5 expression was significantly positively correlated with NEUROD6 and NRN1, whereas correlated with negatively CD163, ITPKB, and AQP1." (PMID 36568274, 2022).
brain diseases (2 papers, 2022 to 2023). "Future studies may provide further molecular insights into the role of CD163 in brain diseases, and the mechanisms underpinning the gender dimorphism." (PMID 38092806, 2023).
gastrointestinal tumors (2 papers, 2020 to 2022). "For example, CD163 and CD206 are common M2-associated markers, but TAMs highly expressing CD163 and CD206 in gastrointestinal tumors or ovarian ascites were found to be functionally equivalent to M1-like TAMs with regard to stimulating T cell activity." (PMID 32849616, 2020).
inflammatory myopathies (2 papers, 2020 to 2024). "We selected four up-regulated genes for general myopathy (MGST1, AOX1, FASN, PRKCD), CD163 for IBM, and CYP4B1 for titinopathy, aiming to validate their actual expression in our local muscles." (PMID 38600180, 2024). "Both the absolute numbers of CD68+ and CD163+ cells, and the ratio of CD163+ and CD68+ cells, were higher in the groups with inflammatory myopathies, compared to controls." (PMID 32936839, 2020). "In this study, the CD163+ macrophages constituted a small fraction of all macrophages (CD68+) in control muscle, but their relative ratio to CD68+ macrophages was increased in inflammatory myopathies." (PMID 32936839, 2020).
vasculopathy (2 papers, 2022 to 2026). "A SARS-CoV-2 viral protein was demonstrated in a subset of cases and a linear positive correlation was observed between ACE2 and CD61/CD163 expression levels, representing the inflammatory cascade and vasculopathy in COVID-19 disease, respectively." (PMID 35260724, 2022).
animal disease (1 paper, 2024). "A representative study in animal disease resistance breeding is the gene editing of pigs to disrupt the PRRSV receptor CD163, which inhibits PRRSV infection without affecting the growth and development of pigs." (PMID 38512977, 2024).
CNS tumors (1 paper, 2025). "Additionally, these previous studies did not classify patients based on the latest WHO classification of CNS tumors, which could further influence the interpretation of the prognostic role of CD163 and COL3A1." (PMID 40427760, 2025).
head and neck tumours (1 paper, 2021). "The association of infiltrating macrophages with a poor prognosis, demonstrated by CD68 and/or CD163 immunophenotyping, has been previously reported in a number of head and neck tumours, but infrequently in selective series of OP-SCCs." (PMID 33769181, 2021).
CD163 also shares sentences with these, for which no sentence is quoted: portal hypertension (12 papers); metabolic syndrome (10); liver cirrhosis (9); alcoholic hepatitis (7); hyperferritinemia (7); chronic lymphocytic leukaemia (6); neurological diseases (6); Classical Hodgkin Lymphoma (5); Crohn disease (5); Gaucher disease (5); gestational diabetes (5); non-alcoholic fatty liver disease (5); non-alcoholic steatohepatitis (5); viral hepatitis (5); chronic hepatitis C (4); Hematuria (4); infarction (4); Abdominal obesity (3); bacterial pneumonia (3); brain injury (3); brain tumors (3); inflammatory bowel disease (3); pemphigus vulgaris (3); polymyositis (3); systemic juvenile idiopathic arthritis (3); Thrombocytopenia (3); acute-on-chronic liver failure (2); Alcohol-Use Disorder (2); alcoholic cirrhosis (2); alcoholic liver diseases (2).
A further 218 diseases each share a sentence with CD163 in 2 papers or fewer.